PFKFB3 (6-phosphofructo-2-kinase/fructose-2,6-biphosphatase 3)
Diseases named in the same sentence as PFKFB3 in open-access papers (continued):
Sharing a sentence is not in itself a finding about the gene and the disease.
esophageal squamous cell carcinoma (7 papers, 2020 to 2025). Esophageal squamous cell carcinoma (ESCC) is a type of esophageal carcinoma (EC) that can affect any part of the esophagus, but is usually located in the upper or middle third. "In conclusion, our research findings indicate that the loss of PFKFB3 can increase the resistance of different human esophageal squamous cell carcinoma cell lines to 5-FU through various pathways." (PMID 40427135, 2025). "In our study, we investigated the potential role of PFKFB3 in 5-FU resistance in human esophageal squamous cell carcinoma and revealed its possible impact on the response of cancer cells to treatment." (PMID 40427135, 2025). "In summary, we can be certain that the loss of PFKFB3 increases the resistance of KYSE-70, KYSE-270 and KYSE-150 esophageal squamous cell carcinoma cells to 5-FU." (PMID 40427135, 2025). "A recent study reports that lncRNA AGPG enhances glycolysis activity and promotes tumor growth via maintaining PFKFB3 protein stability in esophageal squamous cell carcinoma (ESCC)." (PMID 33390824, 2021). "For example, lncRNA AGPG regulates PFKFB3-mediated tumour glycolytic reprogramming in oesophageal squamous cell carcinoma (ESCC)." (PMID 36639695, 2023). "Besides, it was reported that lncRNA AGPG could bind to and stabilize PFKFB3 to promote cell proliferation in esophageal squamous cell carcinoma." (PMID 34601496, 2021). "For instance, lncRNA AGPG, through binding to PFKFB3 and then enhancing PFKFB3 stability, has a great influence in promoting glycolysis and cell proliferation, thereby facilitating the evolution of esophageal squamous cell carcinoma (ESCC)." (PMID 37620336, 2023). "Here, the authors identify a long noncoding RNA in esophageal squamous cell carcinoma, AGPG, which interacts with PFKFB3 and promotes its stability, leading to increased glycolysis and proliferation." (PMID 32198345, 2020).
head and neck squamous cell carcinoma (7 papers, 2017 to 2024). A squamous cell carcinoma that arises from any of the following anatomic sites: lip and oral cavity, nasal cavity, paranasal sinuses, pharynx, larynx, and salivary glands. "The blockage of PFKFB3 decreases tumor growth and metastasis in head and neck squamous cell carcinoma (HNSCC)." (PMID 37919747, 2023). "The mRNA expression level of PFKFB3 was markedly elevated in tumor tissues of colon adenocarcinoma (COAD), cholangiocarcinoma (CHOL), head and neck squamous cell carcinoma (HNSC), stomach adenocarcinoma (STAD), and thyroid carcinoma (THCA) compared with the respective non-tumor tissues." (PMID 37253634, 2023). "However, whether PFKFB3 is overexpressed in head and neck squamous cell carcinoma (HNSCC) tissues remains unknown." (PMID 28061878, 2017).
liver fibrosis (7 papers, 2020 to 2025). "In the present study, ACBA treatment significantly reduced the expression of PFKFB3 in the CCl4-induced mice hepatic fibrosis tissues." (PMID 41375167, 2025). "Liver fibrosis develops after steatosis, since the activation of PFKFB3 produces glycolytic reprogramming." (PMID 40160973, 2025). "PFKFB3 plays a crucial role in the glycolytic process and serves as a critical regulator of macrophage glycolysis, contributing to the progression of liver fibrosis." (PMID 41375167, 2025). "Immunofluorescence staining revealed that PFKFB3 expression was low in normal liver tissue but significantly increased in liver fibrosis tissue of the model group." (PMID 41375167, 2025). "The rs117719091-related gene PFKFB3 can induce glycolysis and activate hepatic stellate cells to promote liver fibrosis, and the knockdown of PFKFB3 inhibited HCC growth by damaging DNA repair function, leading to G2/M phase arrest and apoptosis." (PMID 38003606, 2023).
neuroblastoma (7 papers, 2012 to 2022). Neuroblastoma (NB) is the most common solid, extracranial childhood tumor. "Furthermore, the association of PFKFB3 expression with PFKFB4 level determines the significance of PFK-2 in predicting the prognosis of neuroblastoma, indicating the need to further investigate the effects of these two PFK-2 isoenzymes." (PMID 36276846, 2022). "Here, we measured the expression levels of miR-34a, the tRNAiMet precursor, and tRiMetF31 in neuroblastoma cell lines, and correlated tRiMetF31 levels with PFKFB3 levels." (PMID 35454815, 2022). "Both miR-34a and a 31-nt tRNAiMet fragment (tRiMetF31) derived from miR-34a-guided cleavage were downregulated in 4 examined neuroblastoma cell lines inversely correlated with the levels of its direct target, the PFKFB3 protein." (PMID 35454815, 2022). "In another neuroblastoma line, SK-N-AS, Western blot analysis showed that 12.5 and 50 nM WT-tRiMetF31 inhibited PFKFB3 expression." (PMID 35454815, 2022). "As expected, Western blot analysis indicated that PFKFB3 was overexpressed in 4 neuroblastoma cell lines, and its expression levels were closely correlated with that of tRiMetF31." (PMID 35454815, 2022). "Even though this is the first report of an inverse correlation between miR-34a/tRiMetF31 and PFKFB3 in neuroblastoma cell lines, it is essential to see the relationship in a large cohort of tissue sections." (PMID 35454815, 2022). "In this study, miR-34a and its guided tRNAiMet-cleaved fragment tRiMetF31 were downregulated, whereas PFKFB3, a direct target of tRiMetF31, was overexpressed in all examined neuroblastoma cell lines (n = 4)." (PMID 35454815, 2022). "Undoubtedly, attention should be paid to the fact that in the case of neuroblastoma solely high expression of isoenzyme PFKFB3 correlates with poor prognosis whereas solely high expression of PFKFB4 is a positive prognostic factor for these patients." (PMID 31754349, 2019). "Our findings revealed a key role of tRiMetF31, a novel component of the miR-34a tumor suppressor network, in suppressing proliferation and angiogenesis of neuroblastoma cells, supporting the application of target molecules miR-34a, tRiMetF31, and PFKFB3 in therapeutic intervention for neuroblastoma." (PMID 35454815, 2022). "What’s more, it seems that in neuroblastoma the prognostic value of PFK-II may be dependent on the relation between PFKFB3 and PFKFB4 isoenzyme expression, indicating that further studies analyzing the role of both cancer specific PFK-II isoenzymes are highly desired." (PMID 31754349, 2019). "In order to determine the influence of PFKFB3/4 co-expression on survival rate, the gene expression data were downloaded (GSE62564) and neuroblastoma patients were divided on four groups based on the median PFKFB3/PFKFB4 expression, as described in Materials and Methods." (PMID 31754349, 2019). "Interestingly, three out of four neuroblastoma cell lines (IMR-5, IMR-32, and SK-N-AS) overexpressed PFKFB3, which may be attributed to the downregulation of tRiMetF31." (PMID 35961977, 2022). "However, neuroblastomas with both high PFKFB3 expression and high PFKFB4 co-expression showed a 1.69 hazard ratio, indicating that PFKFB4 may offset negative effects caused by PFKFB3." (PMID 34831136, 2021). "Interestingly, although different tested concentrations of WT-tRiMetF31 apparently attenuated PFKFB3 expression, they did not affect the proliferation of IMR-32 neuroblastoma cells." (PMID 35454815, 2022). "The worst survival prognosis could be observed for the patients with the dominant PFKFB3 expression (G3 group), which clearly indicates that low expression of PFKFB4, and high expression of PFKFB3 at the same time has a negative impact on the survival of neuroblastoma patients." (PMID 31754349, 2019).
type 1 diabetes (7 papers, 2021 to 2025). "Researchers have shown that UNC13B, PFKFB3, FCN1 and SLC11A1 were diagnostic markers for type 1 diabetes." (PMID 36837510, 2023). "Furthermore, as we and others have previously shown, PFKFB3 upregulation can be detected in conditions of metabolic stress, such as in type 1 diabetes in the endothelium and in hepatocytes." (PMID 40002359, 2025). "In a previous study, PFKFB3 had been linked previously to type 1 diabetes; compared to nondiabetic, type 1 diabetes individuals had a larger proportion of β-cells that expressed PFKFB3." (PMID 38741114, 2024). "Moreover, the rate of conversion of fructose-6-phosphate to fructose-1,6-bisphosphate is increased in type 1 diabetes by activating PFKFB3, increasing pyruvate production." (PMID 36430204, 2022).
colitis (6 papers, 2019 to 2026). Inflammation of the colon. "Our study provides an integrative perspective on intestinal ecological shifts arising from macrophage-specific PFKFB3 deficiency in colitis, revealing its novel regulatory microbiota role." (PMID 41378888, 2026). "The role of PFKFB3 on colitis and gut microbiota was investigated by deficiency of PFKFB3 in macrophages (PFKFB3fl/flLyz2-Cre) mice." (PMID 41378888, 2026). "Our findings demonstrate that macrophage-specific PFKFB3 deficiency correlates with enhanced Faecalibaculum genus presence and colitis mitigation." (PMID 41378888, 2026). "Furthermore, in neutrophil-deficient mice, macrophage-specific PFKFB3 deletion still alleviates colitis, solidifying its role as a positive regulator within macrophages." (PMID 41378888, 2026). "Overall, these findings suggest that the gut microbiota in PFKFB3-deficient macrophages mice may involve extensive host-microbial interactions in mitigating DSS-induced colitis." (PMID 41378888, 2026). "Additionally, PFKFB3 deficiency shifts intestinal bacterial communities, leading to a Faecalibaculum-dominated beneficial microenvironment that can be horizontally transmissible to co-housed WT mice, reducing experimental colitis susceptibility." (PMID 41378888, 2026). "The expression of PFKFB3 was significantly upregulated in the colon of both human UC cohorts and colitis mice." (PMID 41378888, 2026). "Pharmacological inhibition of PFKFB3 by 3-(3-pyridinyl)-1-(4-pyridinyl)-2-propen-1-one (3PO) diminished the severity of colitis." (PMID 41378888, 2026). "Our findings indicate an upregulation of PFKFB3 in colitis-affected colonic tissue, and the deletion of PFKFB3 in macrophages imparts protection against intestinal inflammation through the modulation of gut microbiota." (PMID 41378888, 2026). "Our work underscores macrophage-derived PFKFB3’s significant impact on disease progression within DSS-induced colitis models by modifying gut microbiota composition." (PMID 41378888, 2026). "PFKFB3 expression was upregulated in the colon of both ulcerative colitis (UC) patients and colitis mice, and this differential expression was predominantly contributed by colonic lamina propria macrophages." (PMID 41378888, 2026). "Collectively, these findings indicate that PFKFB3 expression is markedly enhanced in activated colitis." (PMID 41378888, 2026). "While our research confirms PFKFB3’s therapeutic potential in colitis, it highlights distinctive mechanistic differences worth examining." (PMID 41378888, 2026). "Given the critical role of PFKFB3 in colitis, we prompted further investigation into the cellular localization of PFKFB3 expression within the colon." (PMID 41378888, 2026). "Employing conditional knockout mice, we identified a novel functional mechanism whereby PFKFB3 modulates colitis via myeloid cells." (PMID 41378888, 2026). "In this study, we demonstrated that PFKFB3 ablation in macrophages alleviated experimental colitis by reshaping the microbial community." (PMID 41378888, 2026). "To evaluate PFKFB3 expression in colitis, we analyzed publicly available data sets from the GEO database." (PMID 41378888, 2026). "This study exhaustively examines the role of PFKFB3, a pivotal glycolysis regulator, in experimental colitis." (PMID 41378888, 2026). "qPCR analysis showed that Pfkfb3 is expressed higher during colitis compared to healthy controls in the T cell transfer model for colitis and dextran sulfate sodium (DSS)-induced colitis." (PMID 36405760, 2022). "Concordantly, inhibition of PFKFB3 decreases the expression of chemokines and pro-inflammatory cytokines in intestinal fibroblasts and decreased colitis severity in two mouse models for IBD." (PMID 36405760, 2022). "Our results show that inhibition of PFKFB3 indeed hampers the inflammation in DSS-induced colitis, simultaneously also decreasing the number of activated/fibrotic stromal cells (highlighted by reduced levels of collagen, α-SMA, and vimentin)." (PMID 36405760, 2022).
colitis (continued). "Our data now show that inhibition of PFKFB3 can also reduce colitis in mice and restore intestinal stromal homeostasis." (PMID 36405760, 2022). "3PO treatment significantly reduced PFKFB3 protein level during DSS-induced colitis." (PMID 41378888, 2026). "Thus, our study focused on elucidating the cellular sources and functional consequences of PFKFB3 upregulation during colitis’ acute inflammatory phase, while Zhou’s work examined PFKFB3’s role in fibroblast-mediated tissue repair during later stages." (PMID 41378888, 2026). "Given the pronounced upregulation of PFKFB3 expression in myeloid cells, particularly macrophages and the central role of innate immune cells in colitis, we generated myeloid-specific PFKFB3 knockout mice by crossing PFKFB3fl/fl mice with Lyz2-Cre mice (PFKFB3fl/flLyz2-Cre)." (PMID 41378888, 2026). "Thus, it is reasonable to infer that 3PO has significant potential to relieve colitis and revealed that PFKFB3 intrinsically aggravated DSS colitis." (PMID 41378888, 2026). "Knockout of PFKFB3 in macrophages significantly alleviated DSS-induced colitis." (PMID 41378888, 2026). "In summary, our data provide evidence for the role of the PFKFB3 in macrophages in colitis." (PMID 41378888, 2026). "Taken together these data show that PFKFB3 inhibition can reduce DSS-induced colitis in mice." (PMID 36405760, 2022). "To better understand how PFKFB3 could modulate intestinal inflammation, we explored its role by taking advantage of experimental models of colitis, such as DSS and T cell transfer." (PMID 36405760, 2022). "Moreover, blockade of PFKFB3 in animal models of RA, psoriasis and colitis has led to resolution of inflammation." (PMID 31555281, 2019). "Thus, our data provide novel insight into the management of PFKFB3 in macrophages during colitis in spite of the potential mechanisms that support the inhibition of pro-inflammatory response remaining partially unknown." (PMID 41378888, 2026). "Our study observed that 3PO, a specific PFKFB3 inhibitor, alleviated symptoms and histological damage in DSS-induced colitis." (PMID 41378888, 2026). "Given that 3PO is a well-established inhibitor of PFKFB3 both in vivo and in vitro, we investigated its role in a DSS-induced murine colitis model." (PMID 41378888, 2026). "In the present study, we demonstrated an enhanced expression of PFKFB3 in colonic tissues of UC patients and DSS-induced colitis." (PMID 41378888, 2026). "Through our study, we affirmed increased PFKFB3 expression in lamina propria cells and macrophages in DSS-induced colitis." (PMID 41378888, 2026). "The results showed that, compared to the DSS‐induced colitis model group, EcN‐T treatment significantly downregulated the expression of HIF‐1α, GLUT1, and PFKFB3, which was consistent with the results of the volcano plot analysis." (PMID 41244343, 2025). "Mechanistically, overexpression of PFKFB3 induced phospho-p65 and promoted the expression of IL-1β and TNF-α in the development of colitis and CAC." (PMID 36016583, 2022). "Flow cytometry data also showed that the percentage of PFKFB3 positive cells and the mean fluorescence intensity increased in stromal cells in DSS-induced colitis." (PMID 36405760, 2022). "Mechanistically, overexpression of PFKFB3 induced phospho-p65 and promoted the expression of IL-1β and tumor necrosis factor alpha (TNF-α) in the development of colitis and CAC." (PMID 36016583, 2022). "Taken together these data reveal that inhibition of PFKFB3 activity reduces stromal accumulation, activation, and collagen deposition, accompanied by decreased intestinal inflammation in a DSS- induced colitis model." (PMID 36405760, 2022). "In summary, we found that PFKFB3 is highly expressed in stromal cells in IBD and that inhibition of PFKFB3 reduces inflammatory cytokine secretion by fibroblasts in vitro and attenuates in vivo experimental models of colitis." (PMID 36405760, 2022).
COVID-19 (6 papers, 2021 to 2025). A disease caused by infection with severe acute respiratory syndrome coronavirus 2. "Metabolic interventions targeting pathways like 6-Phosphofructo-2-kinase/fructose-2,6-bisphosphatase 3 (PFKFB3) inhibition may prove particularly valuable for managing COVID-19-associated neutrophilia and its complications." (PMID 41141324, 2025). "Interestingly, SERPINA1 (encoding protease inhibitor α-1 antitrypsin) and PFKFB3 (encoding phosphofructokinase, a key regulator of glycolysis) were suppressed in COVID-19 neutrophils, suggesting divergence in granule-associated enzyme composition and metabolic states." (PMID 34782790, 2022). "RNA expression of ICAM1 and PFKFB3 in the blood plasma of patients with severe COVID-19 and healthy controls was measured by qRT-PCR." (PMID 33520118, 2021). "Expression of ICAM1 and PFKFB3 was significantly induced in severe-COVID-19 patients compared with that in healthy controls." (PMID 33520118, 2021). "ICAM1 and PFKFB3 were the most significantly upregulated genes in our meta-analysis and could be employed as biomarkers in patients with severe COVID-19." (PMID 33520118, 2021). "Our meta-analysis showed that expression of ICAM1 and PFKFB3 was increased in COVID-19 patients." (PMID 33520118, 2021). "In addition, PFKFB3 was also upregulated in myeloid blood cells from critically ill COVID-19 patients." (PMID 34660743, 2021). "Lung cells from COVID-19 patients show expression of HIF1α, TLR2, TLR4, PFKFB3, CXCR1, −2 and −4, SOD2, PLAUR and other genes expressed in immature myeloid cells." (PMID 33345622, 2021). "HIF-1α can regulate the activity of genes related to glucose transport and processing (LDH-A, PFKFB3, GLUT-1, PKM2), which seems to be overexpressed in monocytes from COVID-19 patients, but not at the same intensity as influenza virus and RSV-infected monocytes." (PMID 33716771, 2021).
malignant pleural mesothelioma (6 papers, 2019 to 2023). A malignant neoplasm that arises from mesothelial cells in the pleura and shows a diffuse growth pattern. "Very recently, it has been shown that 6-phosphofructo-2-kinase/fructose-2,6-biphosphatase 3 (PFKFB3) plays a crucial role in the maintenance of malignant pleural mesothelioma CSCs, and the PFKFB3 inhibitor PFK158 reduced CSC-mediated xenograft growth in vivo." (PMID 37190033, 2023). "As a small molecular antagonist of PFKFB3, PFK158 can mimic genetic inhibition of PFKFB3 (thus inhibiting glycolytic activity), arrest tumor cells in G0/G1 phase, and promote cell death as well as enhance chemotherapy in malignant pleural mesothelioma." (PMID 35155224, 2022). "PFK158 is a PFKFB3 inhibitor that mimics genetic inhibition of PFKFB3 in malignant pleural mesothelioma." (PMID 35155224, 2022). "Nuclear targeting PFKFB3 not only increases cell proliferation, our former study also showed it played a promotional role in regulating autophagy in renal cancer cells, and PFKFB3 deprivation reduced autophagy in rhabdomyosarcoma cells and malignant pleural mesothelioma cells." (PMID 31671668, 2019). "Moreover, it has been shown that both PFKFB3 ablation and inhibition with PFK158 trigger late endosome formation in malignant pleural mesothelioma by increasing the interaction of Rac1 with Rab7, where Rab7 plays an important role in the final maturation of late autophagic vacuoles." (PMID 34359849, 2021).